TTF2 (transcription termination factor 2)
Description:
DsDNA-dependent ATPase which acts as a transcription termination factor by coupling ATP hydrolysis with removal of RNA polymerase II from the DNA template. May contribute to mitotic transcription repression. May also be involved in pre-mRNA splicing.
Synonyms: HuF2; ZGRF6
Tractability: PROTAC: UniProt records ubiquitination sites on it; ubiquitination databases record sites on it; its protein half-life has been measured.
Gene: Protein-coding gene on chromosome 1 (117,060,294 to 117,107,453, forward strand). Ensembl gene ENSG00000116830.
Subcellular location: Cytoplasm; Nucleus
Subcellular location (Human Protein Atlas): Cytosol
Gene Ontology:
Molecular function: ATP hydrolysis activity; ATP-dependent activity, acting on DNA; protein binding; ATP binding; zinc ion binding
Biological process: DNA-templated transcription termination; termination of RNA polymerase II transcription
Cellular component: cytosol; transcription elongation factor complex; cytoplasm; nucleus
Genetic constraint (gnomAD): Loss-of-function variants: 105 observed, 143.3 expected, observed/expected ratio (o/e) 0.73, 90% interval 0.62 to 0.86. The upper end of that interval is the gene's LOEUF score, 0.86, which puts it in group 3 of 6, group 1 being the genes least tolerant of losing a copy. Missense variants: 1,322 observed, 1,441.4 expected, observed/expected ratio (o/e) 0.92, 90% interval 0.88 to 0.96. Synonymous variants: 483 observed, 535.38 expected, observed/expected ratio (o/e) 0.9, 90% interval 0.84 to 0.97.
Homologues: Orthologues: chimpanzee TTF2 (99% identical), macaque TTF2 (96% identical), rabbit TTF2 (77% identical), pig TTF2 (76% identical), mouse Ttf2 (71% identical), Drosophila melanogaster lds (30% identical). Paralogues in human: HLTF (22% identical), BTAF1 (17% identical), CHD4 (16% identical), CHD5 (16% identical), RAD54B (16% identical), SRCAP (16% identical), ATRX (15% identical), INO80 (15% identical), CHD3 (15% identical), SMARCA2 (15% identical), SMARCA4 (15% identical), CHD7 (15% identical), and 18 more.
Diseases named in the same sentence as TTF2 in open-access papers:
TTF2 is named in the same sentence as 24 diseases in open-access papers, as found by Europe PMC text mining. Sharing a sentence is not in itself a finding about the gene and the disease. The quoted sentences say what the papers report.
thyroid agenesis (6 papers, 2009 to 2024). "Mutation in the gene encoding human TTF-2 is associated with thyroid agenesis, cleft palate, and choanal atresia." (PMID 39684471, 2024). "“Thyroid transcription factor 2” (TTF-2) mutation is associated with thyroid agenesis and other defects." (PMID 26634164, 2015). "A mutation in thyroid transcription factor 2 (TTF-2) causes a syndrome of thyroid dysgenesis, choanal atresia, cleft palate and spiky hair also known as Bamforth-Lazarus syndrome." (PMID 20537182, 2010). "Further, while the exact cause of some cases of thyroid dysgenesis is known, e.g., a mutation in the TTF-2 gene, mutations in genes encoding such transcription factors important in thyroid gland development have been found in only 2% of cases." (PMID 20537182, 2010). "Missense mutations in TTF-2 have been reported in conjunction with thyroid agenesis and congenital hypothyroidism in humans." (PMID 19197348, 2009). "Pax-8, Ttf-1, and Ttf-2 are transcription factors crucial to thyroid organogenesis and their absence results in varying degrees of thyroid dysgenesis." (PMID 33806425, 2021). "Additionally, 21.21% (28/132) of mutations were related to thyroid dysgenesis [TSHR (n = 19), TTF1 (n = 5), TTF2 (n = 1), PAX8 (n = 2), and NKX2-5 (n = 1)]." (PMID 30420871, 2018).
thyroid cancer (4 papers, 2012 to 2025). "Another notable gene, TTF2, a thyroid-specific transcription factor, has been implicated in the pathogenesis of multiple cancers, including thyroid carcinoma." (PMID 40427243, 2025). "Therefore, we decided to assess the potential contribution of TTF-1 and TTF-2 genes as sources of genetic susceptibility to thyroid cancer in this particular group." (PMID 22481925, 2012). "FOXE1 or thyroid transcription factor 2 (TTF-2) belongs to the ‘forkhead’ gene family and is involved in promoting the migration process or in repressing differentiation of the thyroid follicular cells until migration has occurred and has been associated with thyroid cancer." (PMID 23251661, 2012).
Papillary Thyroid Cancer (3 papers, 2012 to 2021). "Thyroid transcription factor 2 (TTF2) is highly expressed in papillary thyroid cancer." (PMID 33658396, 2021).
thyroid (3 papers, 2014 to 2023). "According to previous reports, the cause of CH in approximately 80%–85% of patients is thyroid dysgenesis (including agenesis, ectopy, and hypoplasia), which is related to gene mutations in TSHR, PAX8, TTF1/NKX2-1, and TTF2/FOXE1." (PMID 37252044, 2023). "And mutations in thyroid transcription factors TTF-1, TTF-2 and PAX-8 have been implicated in thyroid dysgenesis and abnormal migration of the thyroid bud." (PMID 24748408, 2014).
cleft palate (2 papers, 2012 to 2024). Cleft palate is a fissure type embryopathy that affects the soft and hard palate to varying degrees. "It was previously demonstrated that complete deletion or partial loss of its function may lead to cleft palate in both animal models (TTF-2−/− mouse) and human beings." (PMID 22304410, 2012). "In our study, we found that overexpression of TTF-2 caused the cleft palate." (PMID 22304410, 2012). "TTF-2 null mice (TTF-2−/−) also exhibit cleft palate, suggesting its involvement in the palatogenesis." (PMID 22304410, 2012). "Our study indicates that TTF-2 may be involved in the palatogenesis and pathogenesis of cleft palate." (PMID 22304410, 2012). "We demonstrated that overexpression of TTF-2 during the palatogenesis may contribute to cleft palate." (PMID 22304410, 2012).
anaplastic thyroid carcinoma (1 paper, 2025). "It induces the expression of differentiation markers (TTF1, TTF2, Pax8, and sodium/iodide symporter (NIS)) in anaplastic thyroid carcinoma through the activation of Notch1 signaling, thereby suppressing cell growth." (PMID 40943396, 2025). "Resveratrol, for example, has been shown to induce redifferentiation markers (TTF1, TTF2, Pax8, NIS) in anaplastic thyroid carcinoma cells through the activation of Notch1 signaling." (PMID 40943396, 2025).
Bamforth syndrome (1 paper, 2012). "In humans, mutations of the gene encoding for TTF-2 result in Bamforth syndrome, characterized by thyroid agenesis, cleft palate, spiky hair and choanal atresia." (PMID 22304410, 2012). "In humans, mutations of the gene encoding for thyroid transcription factor-2 (TTF-2 or FOXE1) result in Bamforth syndrome." (PMID 22304410, 2012).
breast carcinoma (1 paper, 2020). "On the other hand, low expression of TTF2, ABCC2, FLOT2, and NLRP2 was correlated with poor prognosis in HER2-positive breast cancer patients, whereas their low expression was correlated with better prognosis in the overall METABRIC cohort." (PMID 32640677, 2020).
gastric cancer (1 paper, 2020). A primary or metastatic malignant neoplasm involving the stomach. "The functions of ZNF823, ZFP69B, SP6, KYNU, KIF21B, and TTF2 have not been reported in gastric cancer." (PMID 32848739, 2020).
gastric tumor (1 paper, 2021). "Associated to mucins, too, is the family of trefoil factors, including the gastric tumor suppressors TFF1 and TTF2, which are co-localized with MUC5AC and MUC6, respectively; and TFF3, which is typically not secreted by gastric mucosa but, like MUC2, by goblet cells." (PMID 34227026, 2021).
large cell lung carcinoma (1 paper, 2021). "TTF2 expression was significantly upregulated in large cell lung carcinoma tissues (fold change=2.064, p=5.80E-05) compared to the normal lung tissues in the Hou lung dataset." (PMID 33658396, 2021).
neuroblastoma (1 paper, 2017). Neuroblastoma (NB) is the most common solid, extracranial childhood tumor. "Interestingly, several sequence alterations in other genes involved in chromatin regulation in neuroblastoma have been found, including EP300, CREBBP, TTF2, KDM5A, CHD9, and gene IKZF1, which might undergo somatic mutations and promote NB occurrence." (PMID 28055978, 2017).
thyroid tumor (1 paper, 2021). A benign or malignant neoplasm affecting the thyroid gland. "Forkhead factor E1 (FOXE1), also called TTF2 for thyroid transcription factor, was firstly isolated from cDNA of mouse and modified the development of the thyroid gland and their expression in thyroid tumors through encoding thyroid-specific transcription factors." (PMID 34950210, 2021).
cancer (6 papers, 2012 to 2025). A tumor composed of atypical neoplastic, often pleomorphic cells that invade other tissues. "Dysregulation and variants of TTF1 and TTF2 can cause many diseases, including cancers." (PMID 26356687, 2015). "Especially, 7 of ATPCRs showed a significant overexpression in multiple cancer types, including TTF2 (n = 6), RAD54L (n = 4), ACTL6A (n = 4), CHD7 (n = 3), HELLS (n = 3), HLTF (n = 3), and ACTR5 (n = 3)." (PMID 35789070, 2022). "According to the data, numerous genes (such as H2AFX, CDKN2A, TTF2, IKBKE, and UBE2I) were markedly upregulated in many cancer types, while some genes (such as ARRB1, LMO3, KHDRBS2, CIRBP, and RALYL) were remarkably downregulated in multiple cancer types." (PMID 35003212, 2021).
tumor (3 papers, 2021 to 2025). "We stratified patients by shortest vs. longest TTF2 and analyzed 20 treatment-naïve tumor tissues samples via transcriptomics and immunohistochemistry." (PMID 40696453, 2025). "Expression levels of the key genes TNS2, LRIF1, STK26, and TTF2 showed marked differences, exhibiting substantially elevated expression in tumor tissues versus normal tissues." (PMID 40212965, 2025). "In a detailed examination of 114 paired samples from the TCGA–LUAD cohort, significant variations were observed in the expression of LRIF1, STK26, TNS2, and TTF2 between tumor and normal tissues, with p values less than 0.001." (PMID 40212965, 2025). "Moreover, TTF2 expression correlates with the tumor stages of NSCLC patients." (PMID 33658396, 2021). "The mRNA and protein expression levels of UHRF1, EZH2, TTF2, WHSC1 and RAD54L significantly correlated with tumor stage in NSCLC patients." (PMID 33658396, 2021). "Furthermore, expression levels of UHRF1, EZH2, TTF2, WHSC1 and RAD54L transcripts correlated significantly with the tumor stages of NSCLC patients (P<0.05)." (PMID 33658396, 2021). "Therapy-naïve PDAC tumor specimens (resections and biopsies) of 10 patients per group from the PREDICT trial were evaluated representing either short (S-TTF2) or long (L-TTF2) second-line treatment durations, i.e., the bottom and top 40th-percentiles of TTF2 values, respectively." (PMID 40696453, 2025).
TTF2 also shares sentences with these, for which no sentence is quoted: choanal atresia (1 paper); colon cancer (1); congenital hypothyroidism (1); glioma (1); hypothyroidism (1); mesothelioma (1); multinodular goiter (1); Obesity (1); Zinc deficiency (1).